ATP8B4 (ATPase phospholipid transporting 8B4 (putative))
Description:
Component of a P4-ATPase flippase complex which catalyzes the hydrolysis of ATP coupled to the transport of aminophospholipids from the outer to the inner leaflet of various membranes and ensures the maintenance of asymmetric distribution of phospholipids. Phospholipid translocation also seems to be implicated in vesicle formation and in uptake of lipid signaling molecules (Probable).
Synonyms: KIAA1939; ATPIM
Tractability: Antibody: UniProt places it where antibodies can reach, with high confidence; its Gene Ontology location is reachable by antibodies, with high confidence; UniProt predicts a signal peptide or a membrane-spanning region.
Gene: Protein-coding gene on chromosome 15 (49,858,238 to 50,182,817, reverse strand). Ensembl gene ENSG00000104043.
Subcellular location: Cell membrane; Golgi apparatus
Subcellular location (Human Protein Atlas): Nucleoplasm; Vesicles; Cytosol
Pathways (Reactome):
Immune System: Neutrophil degranulation
Transport of small molecules: Ion transport by P-type ATPases
Gene Ontology:
Molecular function: protein binding; ATP binding; ATP hydrolysis activity; ATPase-coupled intramembrane lipid transporter activity; magnesium ion binding; nucleotide binding
Biological process: Golgi organization; phospholipid translocation; phospholipid transport
Cellular component: Golgi apparatus; phospholipid-translocating ATPase complex; plasma membrane; specific granule membrane; tertiary granule membrane; trans-Golgi network; cytoplasm; endomembrane system; membrane
Genetic constraint (gnomAD): Loss-of-function variants: 93 observed, 109.07 expected, observed/expected ratio (o/e) 0.85, 90% interval 0.72 to 1.01. The upper end of that interval is the gene's LOEUF score, 1.01, which puts it in group 4 of 6, group 1 being the genes least tolerant of losing a copy. Missense variants: 1,203 observed, 1,241.9 expected, observed/expected ratio (o/e) 0.97, 90% interval 0.92 to 1.02. Synonymous variants: 418 observed, 437.87 expected, observed/expected ratio (o/e) 0.95, 90% interval 0.88 to 1.03.
Homologues: Orthologues: chimpanzee ATP8B4 (99% identical), macaque ATP8B4 (97% identical), dog ATP8B4 (92% identical), pig ATP8B4 (91% identical), rat Atp8b4 (88% identical), rabbit ATP8B4 (87% identical), mouse Atp8b4 (86% identical), guinea pig ATP8B4 (85% identical), tropical clawed frog atp8b4 (78% identical), zebrafish atp8b4 (70% identical), Drosophila melanogaster CG31729 (26% identical), Caenorhabditis elegans tat-5 (25% identical), and 1 more. Paralogues in human: ATP8B2 (70% identical), ATP8B1 (55% identical), ATP8B3 (43% identical), ATP8A2 (39% identical), ATP8A1 (39% identical), ATP10D (35% identical), ATP10A (35% identical), ATP10B (35% identical), ATP11C (33% identical), ATP11A (33% identical), ATP11B (32% identical), ATP9B (27% identical), and 1 more.
Diseases named in the same sentence as ATP8B4 in open-access papers:
ATP8B4 is named in the same sentence as 15 diseases in open-access papers, as found by Europe PMC text mining. Sharing a sentence is not in itself a finding about the gene and the disease. The quoted sentences say what the papers report.
Alzheimer disease (5 papers, 2013 to 2025). A progressive, neurodegenerative disease characterized by loss of function and death of nerve cells in several areas of the brain leading to loss of cognitive function such as memory and language. "Alterations in the functionality of this family of flippases have been associated with multiple diseases and disorders (e.g., variants in ATP8B4 have been associated with Alzheimer’s disease)." (PMID 26625115, 2015). "A significant association between Alzheimer’s disease and the ATP8B4 locus on chromosome 15 was reported." (PMID 23579954, 2013). "Notably, rare damaging variants in ATP8B4 have been linked to an increased risk of Alzheimer disease, which is closely associated with ageing, and early-onset cerebral amyloid angiopathy." (PMID 41004220, 2025). "There was also strong evidence for colocalization between an IEAA-associated locus on chromosome 15 (lead SNP rs12903325), and an eQTL for the lipid transporter gene ATP8B4, which contains variants that have been reported in relation to centenarian status in Italians and Alzheimer’s disease." (PMID 34187551, 2021). "Although a follow-up on this association never occurred, this observation might suggest that mutations in ATP8B4 may predispose to Alzheimer’s disease." (PMID 23579954, 2013). "Multistage gene burden analysis in exome sequencing data from 32,558 individuals identifies rare damaging variants in ATP8B4 and ABCA1 as risk factors for Alzheimer’s disease." (PMID 36411364, 2022). "With the exception of ATP8B4 (Alzheimer’s disease) and ATP10A (insulin resistance in African Americans), thus far none of the human P4 ATPases have been identified as risk genes in GWAS." (PMID 23579954, 2013).
systemic sclerosis (2 papers, 2019 to 2020). A chronic disorder, possibly autoimmune, marked by excessive production of collagen which results in hardening and thickening of body tissues. "ATP8B4, a participant in ATP biosynthesis and phospholipid transport via a variety of potential mechanisms, was found to be a risk factor for systemic sclerosis and pulmonary vascular complications." (PMID 33169786, 2020). "ATP8B4 was recently identified as a risk factor for systemic sclerosis, which is a rare multisystem autoimmune disease." (PMID 31772684, 2019).
inflammatory bowel disease (1 paper, 2022). A spectrum of small and large bowel inflammatory diseases of unknown etiology. "In addition, 4 of the signals detected when CRC was compared with inflammatory bowel disease patients were suggestive: in the HLA region, in the DLGAP2 gene, downstream of the PTCHD3 gene and upstream of the ATP8B4 gene." (PMID 36077729, 2022).
Neonatal sepsis (1 paper, 2021). Systemic inflammatory response to infection in newborn babies. "Hence, the lower methylation levels observed in the promoters of genes involved in neutrophil activation (i.e., ATP8B4, LRG1, TREM1, PRTN3, S100A8, ELANE, and CD177) illustrates the role of DNAm in innate immunity in neonatal sepsis." (PMID 33659006, 2021).
tumor (2 papers, 2022 to 2025). "The results showed that the expression of ACACB, ATP8B4, C14orf28, CIRBP, and DTWD1 were higher in normal tissues, and the content of CDC6, DSP, HMGB3, HNRNPA3P1, PPP1R14C, and TPX2 were higher in tumor tissues." (PMID 35778922, 2022).
ATP8B4 also shares sentences with these, for which no sentence is quoted: glioma (2 papers); autoimmune disease (1); cerebral amyloid angiopathy (1); cervical squamous cell carcinoma (1); channelopathies (1); COVID-19 (1); glioblastoma multiforme (1); Insulin resistance (1); melanoma (1); renal carcinoma (1).